IL6 (interleukin 6)
Diseases named in the same sentence as IL6 in open-access papers (continued):
Sharing a sentence is not in itself a finding about the gene and the disease.
depression (continued). "Genetically-predicted IL-6 was associated with increased risk of schizophrenia in univariable MR (OR=1.24; 95% C.I., 1.05-1.47) and with major depression in MVMR (OR=1.08; 95% C.I., 1.03-1.12)." (PMID 34280516, 2021). "The “usual suspects” associated with depression tend to be elevated interleukins (ILs), interferons (IFNs) and acute phase proteins, including IL-1β, IL-6, IL-2, IFN-γ, tumour necrosis factor alpha (TNF-α) and C-reactive protein (CRP)." (PMID 34816138, 2021). "In a large birth cohort study (ALSPAC), elevated IL-6 levels in childhood were associated with neurovegetative symptoms of depression, including sleep difficulties and fatigue, measured later in adolescence." (PMID 34816138, 2021). "Individuals with MDD also show elevated serum levels of various immune factors such as IL-6 and TNFα, and IL-6 in particular has been implicated in depression across a number of clinical and preclinical studies." (PMID 33935636, 2021). "A previous study from the Avon Longitudinal Study of Parents and Children (ALSPAC) birth cohort reported that higher levels of interleukin (IL-6), a proinflammatory cytokine, at age 9 were associated with risks for depression and psychosis at age 18 years." (PMID 33684738, 2021). "In conclusion, we report evidence for longitudinal, dose-response associations of childhood IL-6 levels with risks for psychosis and depression in adulthood, with the strongest associations for more clinically relevant outcomes." (PMID 33684738, 2021). "On the contrary, the clinical manifestations of severe depression, like psychomotor retardation, are associated with proinflammatory response, that is, high level of IL-6." (PMID 34531719, 2021). "Prenatal PM10 and PM2.5 exposures have been linked to elevated maternal CRP and Il-6 levels and considerable evidence implicates these neuroinflammatory pathways in depression pathophysiology." (PMID 34838014, 2021). "Our study showed that some inflammatory markers, especially CRP and IL-6, appeared to be associated with depression status." (PMID 33064180, 2021). "In the present study, many anti-depressant targets of EMO against depression were associated with the inflammatory response such as IL6, TNF, IL10, CRP, IL1B, CTLA4, ALB and IL2." (PMID 34051074, 2021). "Second, we report some evidence in support of a causal relationship between IL-6 and major depression after controlling for CRP and sIL-2Rα." (PMID 34280516, 2021). "Interleukin (IL)-1β, IL-6, IL-10, monocyte chemoattractant protein-1, tumor necrosis factor-alpha, C-reactive protein, and phospholipase A2 contribute to depression, which is also associated with type 2 diabetes." (PMID 34639601, 2021). "It is also important to investigate if immunological markers beyond CRP and IL-6 are potentially causally associated with depression, and to identify potential cellular drivers for IL-6 dysfunction." (PMID 34135474, 2021). "Produced by macrophages and monocytes at inflammatory sites, in the aged population, elevated IL-6 levels are associated with a higher risk of dementia, depression, rheumatoid arthritis, and cardiovascular disorders." (PMID 33070170, 2021). "Plasma CRP in depression was not only positively associated with plasma levels of inflammatory cytokines (e.g., IL-6, TNF-α, sTNFR2, and IL-1ra), but also correlated with the level of CRP in cerebrospinal fluid." (PMID 34975571, 2021). "Currently, known cytokines associated with depression are IL-1β, IL-6, TNF-α, IFN-γ, c-reactive protein (Müller, 2014)." (PMID 34526897, 2021). "Changes in IL-6 indirectly mediated depression outcome, with metyrapone increasing IL-6 levels and IL-6 increase associated with a poorer outcome on depression." (PMID 33669254, 2021). "Of the various cytokines, the best replicated association with depression has been found for plasma interleukin-6 (IL-6), and to a lesser degree, IL-1β and tumor necrosis factor alpha (TNFα)." (PMID 33903586, 2021).
depression (continued). "Several studies have supported associations of higher CRP or IL-6 levels with increased depression severity." (PMID 34729541, 2021). "We examined potential causality using 1-sample and 2-sample Mendelian randomisation (MR) analyses testing associations of genetically-predicted CRP concentration and IL-6 activity with depression and anxiety." (PMID 34505025, 2021). "In sex-stratified MR analyses, we found evidence that higher genetically-predicted IL-6 activity was associated with increased risk for depressive symptoms, probable depression, and probable GAD in women only." (PMID 34505025, 2021). "A higher decrease in IL-6 levels in this study was associated with a stronger reduction of depression scores." (PMID 34204400, 2021). "In early puerperium, pro-inflammatory cytokines (TNF-α and IL-6), are increased in women who self-report anxiety and depression and are predictors of the consistency and long-term risk of mood disturbance." (PMID 34589733, 2021). "Multiple studies have also found that some subtypes of depression are associated with increased levels of markers of systemic inflammation, such as interleukin 6 (IL-6) and C-reactive protein." (PMID 34468686, 2021). "Higher baseline scores of the Montgomery–Åsberg Depression Rating Scale (MADRS) were associated with a stronger decrease of logIC IL-6 (indicating an increase of GR sensitivity)." (PMID 33447872, 2021). "Elevated pro-inflammatory cytokines, including interleukin-1, interleukin-6, and tumor necrosis factor, have been associated with depression and have been shown to regulate the hypothalamic-pituitary-adrenal axis as well as neurotransmitter release." (PMID 34703799, 2021). "High levels of IL-6 in childhood are associated with an increased risk of depression and psychotic experiences (PEs) in a dose-dependent manner in young adulthood." (PMID 34421539, 2021). "The administration of endotoxin to healthy volunteers caused an increase in the level of IL-6 in the cerebrospinal fluid, which positively correlated with the severity of depressive symptoms consistent with a more severe depression of mood." (PMID 34945157, 2021). "Clinical studies reveal that depression is associated with elevated levels of IL-6 and IL-1β proteins in the cerebrospinal fluid." (PMID 34576218, 2021). "Both TNF-α and IL-6 were reported to be linked to depression pathogenesis; therefore, these cytokines were assessed, in this study, in order to investigate the anti-inflammatory effect of musk." (PMID 34512285, 2021). "Our results are consistent with a previous study from the same birth cohort reporting longitudinal, dose-response associations between childhood IL-6 and risks for psychosis and depression at age 18 years." (PMID 33684738, 2021). "On a genetic level, a recent correlation study based on a large genome-wide association study reported an overlap between CRP levels and depression symptoms as well as an association of upregulated IL-6 with suicidality." (PMID 34279714, 2021). "A single dose of ketamine reduced elevatory serum levels IL-1β and IL-6 to normal in depression-like rats caused by neuralgia." (PMID 34079622, 2021). "A body of evidence suggests that depression is associated with chronic low-grade inflammation, and increased inflammatory cytokine levels including tumour necrosis factor, interleukin-1β and interleukin-6." (PMID 33706839, 2021). "Studies suggest that depression is associated with elevated levels of both pro-inflammatory and anti-inflammatory cytokines, e.g., IL-1β, IL-6, IFN-γ, TNF-α, and C-reactive protein (CRP)." (PMID 33920992, 2021). "Higher circulating IL-6 levels are associated with schizophrenia and depression in cross-sectional and longitudinal studies, and are associated with treatment resistance." (PMID 34280516, 2021). "At the same time, research results suggest that IL-6 levels are negatively associated with BDNF levels in cancer patients with depression." (PMID 34841285, 2021).
depression (continued). "Only one prior study that measured IL-6 found an association with IL-6 and depression in people with type 2 diabetes, whereas two studies did not." (PMID 33064180, 2021). "Our findings that change in sleep time was inversely associated with anxiety, depression, and serum cytokine levels (IL-2, IL-1β, IL-6, TNFα) are in keeping with the consensus of these reviews." (PMID 33598780, 2021). "IL‐6 levels were associated with quantitative scores of the Geriatric Depression Scale (ρ = 0.297, p = .025) in controls." (PMID 33655551, 2021). "Perhaps genetic variants of the genes encoding IL-6 play a role in the response to some drugs used in depression." (PMID 34945157, 2021). "Adjusted logistic regression models showed cross-sectional associations of C-reactive protein and IL-6 with depression." (PMID 33064180, 2021). "This is because we found that genetically predicted increases in IL-6 were associated with an increased risk of schizophrenia and depression, while the association with genetically-predicted increased CRP fully attenuated in schizophrenia." (PMID 34280516, 2021). "We report that raised IL-6 levels in childhood are associated with risks for psychosis and depression at age 24 in a linear dose-dependent fashion." (PMID 33684738, 2021). "Increased peripheral pro-inflammatory cytokines such as TNFα and IL-6 can affect blood-brain barrier permeability, and are implicated in the pathophysiology of depression." (PMID 34351967, 2021). "Cross-sectional associations of inflammatory markers with depression status were tested and showed positive associations with IL-6 and CRP." (PMID 33064180, 2021). "In a meta-analysis of 22 studies (20,791 participants) of the association between depressive symptoms/depressive disorder and inflammation in children and adolescents, IL-6 level was correlated with depressive symptoms." (PMID 34576215, 2021). "For example, one prospective study among 4415 youths (the dataset used for the current analysis) has indicated that higher IL-6 levels at age 9 years were associated with an increased risk of depression at age 18 years." (PMID 32140686, 2020). "Incident depression was significantly associated with increases in IL-1β, IL-6, and IL-8 serum levels in late-life depression." (PMID 32858844, 2020). "Studies have investigated the association between peripheral IL-6 levels and depression in patients who accepted medical treatment." (PMID 32235786, 2020). "Apart from TS total score, CSA was also found to be significantly negatively associated with log IL-6 among participants with depression (r = -0.28, N = 86, p<0.01)." (PMID 32413063, 2020). "About 20–50% of hepatitis C and cancer patients who have undergone interferon-α (IFNα) therapy are estimated to develop clinically significant depression, associated with high serum levels of sIL-2r, TNFα, and IL-6." (PMID 32046139, 2020). "Elevated IL-6 and triglycerides levels in childhood are associated with increased risk of depression in young adulthood." (PMID 30886334, 2020). "The IL-6 effect in depression is further supported by Il6-deficient mice, which were resistant to the development of a depression-like behaviors following exposure to stress." (PMID 32235786, 2020). "Data from the longitudinal Netherlands Study of Depression and Anxiety suggests cross-sectional and bidirectional longitudinal associations between depression and IL-6 levels in blood plasma." (PMID 32858844, 2020). "Elevations in IFN-γ and IL-6 are associated with decreases in tryptophan, the precursor of serotonin, a key neurotransmitter underlying the neurobiology of both depression and PTSD." (PMID 32916852, 2020). "Using prospective birth-cohort data, we reported that higher levels of IL-6 in childhood are associated with an increased risk of developing depression subsequently in early adulthood in a dose-dependent manner." (PMID 31707310, 2020).
depression (continued). "In the present study, trust in partner shows significant association with IL-6 level in participants with clinically significant depression (r = 0.36, p<0.01)." (PMID 32413063, 2020). "A recent study using Mendelian randomization to elucidate shared mechanisms underlying the association of depression and coronary heart disease provided evidence that triglycerides, IL-6 and CRP are causally related to depression." (PMID 32228541, 2020). "A large body of evidence demonstrated that changes in IL-6 levels, both in plasma and in the brain, are implicated in the emergence of depression, although other factors, environmental or genetic in nature, provide an important contribution." (PMID 32732883, 2020). "Fatigue and depression caused by elevated cytokine production, interleukin 6 (IL-6), along with severe weight loss (>10%) and NOD can be early paraneoplastic signs and potential precursors for PC." (PMID 32742851, 2020). "Apart from being associated with depression, levels of IL6 along with IL1 and CRP have been shown to be increased in patients with cognitive impairment and in obese persons, respectively." (PMID 32781663, 2020). "In a cohort of 95 non-depressed hepatitis C patients followed for four months during interferon-alpha therapy, higher pre-treatment IL-6 levels were associated with the following incidence of depression." (PMID 32235786, 2020). "Among the five types of childhood trauma measured in this study, CSA showed the strongest association with IL-6 level in participants with clinically significant depression (r = -0.28, p<0.01)." (PMID 32413063, 2020). "Similar findings were reported in major depression showing significant associations between an immune activation index (based on IL-6 and IL-10) and KOR, MOR and β-endorphin levels." (PMID 32858974, 2020). "We provide evidence that inflammation, particularly the CRP and IL-6/IL-6R pathways, is causally involved in pathogenesis of depression." (PMID 30886334, 2020). "IL-6 is thought to play an important role in the pathogenesis of depression and previously, elevated levels were associated with bad prognosis and worse disease course." (PMID 32858844, 2020). "Depression has been associated with increased levels of interleukin-6 (IL-6), tumor necrosis factor-alpha (TNF-α), and C-reactive protein (CRP)." (PMID 32380710, 2020). "Population-based longitudinal studies including our own work have reported that higher concentrations of CRP or IL-6 in childhood or adult life are associated with increased risk of depression or persistent depressive symptoms subsequently at follow-up." (PMID 30886334, 2020). "Depression at baseline was associated with higher IL-6 levels at baseline and with higher IL-6 levels after the two- and six-year follow-ups." (PMID 32858844, 2020). "High level of IL-6 increases the risk of developing late-life depression and is associated with treatment resistance of depression patients." (PMID 32655450, 2020). "To study the possible mechanism underlying susceptibility of CUMS-induced depression to hyperglycemia, we then detected the hypothalamic inflammatory cytokine-IL-6 and the insulin signaling pathway." (PMID 32655424, 2020). "For example, in patients with major depressive disorder an elevated interleukin (IL)-6 serum level was associated with reduced prefrontal cortical thickness." (PMID 33132923, 2020). "Although many neuroimmune factors have been implicated in depressive disorders, studies in humans suggest that elevation of peripheral IL-6 is one factor that is most consistently observed." (PMID 32518327, 2020). "In summary, our findings indicate that childhood IL-6 levels are associated with specific symptoms of depression in early adulthood." (PMID 30414442, 2019). "This analysis identified a gene co-methylation module (the “Turquoise module”) associated with the interaction between history of depression and inflammatory disorders, as well as with TL and levels of IL-6." (PMID 30650526, 2019).
depression (continued). "For example, in a study implicating 210 non-smoking healthy and unmedicated adult men and women, poor sleep quality was associated with higher values of CRP and IL-6 in women only, after adjustment for age, BMI, and symptoms of depression." (PMID 31287027, 2019). "A systematic review and meta-analysis of 32 studies also supported an association of both CRP and IL-6 with depression in older adults, and it is likely that inflammation leads to depression." (PMID 30995920, 2019). "Based on our study results, we believe that significantly elevated serum concentrations of IL-6 are associated with depression." (PMID 30899619, 2019). "WEC have been found to prevent not only the production of TNF-α and IL-6 in activated brain microglial cells/macrophages, but also neuroinflammation associated with fatigue, depression, and memory impairment in animal studies." (PMID 31394768, 2019). "Both disturbed and curtailed sleep have indeed been shown to increase low-grade inflammation directly and depression is known to be associated with pro-inflammatory cytokines such as interleukin-6." (PMID 29807551, 2019). "For instance, a 2-year prospective study showed that depression was prevalent in patients after ischemic stroke, and IL-6 was positively correlated with the risk of PSD." (PMID 32148646, 2019). "Depression is associated with the pro-inflammatory cytokine (IL-1, IL-6, and TNFα) via regulation of CRF." (PMID 31312123, 2019). "Previous studies have shown an association between religious attendance and lower interleukin-6 levels, an inflammatory marker potentially related to depressive disorders." (PMID 31572245, 2019). "Previous studies have reported an association between religious attendance and decreased levels of interleukin-6, a pro-inflammatory cytokine linked to higher mortality in older adults as well as depression." (PMID 31572245, 2019). "These and other data suggest that IL-6 trans-signaling is associated with treatment resistance in depression." (PMID 29103192, 2018). "Depression is associated with increased concentration of proinflammatory cytokines in circulation, such as IL-1β, IL-6, TNF-α, IFN-γ, and chemokines." (PMID 29351245, 2018). "Secondly, depression is associated with the hyperactivity of immune inflammatory responses as manifested by elevated expression of proinflammatory molecules, such as IL-6 and TNF-α." (PMID 29861834, 2018). "IL-10 and IL-6 are likely to be involved, since IL-10 concentration was associated with depression and Tocilizumab decreased depressive symptoms in the RA patients." (PMID 30148175, 2018). "Further studies are necessary to evaluate the association between high peripheral IL-6 levels and the subsequent risk of developing depression in old age." (PMID 30104698, 2018). "Chronic mild stress has been shown to cause depression‐like behavior and induce the production of inflammatory cytokines such as IL‐1β and IL‐6 in rats." (PMID 29953737, 2018). "Longitudinal studies including our own have shown that elevated IL-6 or CRP levels are associated with increased risks of developing depression and psychosis in future." (PMID 29140226, 2018). "Epidemiological studies based on prospective cohorts suggest, higher IL-6 levels are associated with cognitive symptoms of depression and depression severity subsequently." (PMID 29197507, 2018). "Although human population-based observational studies strongly support an association between IL-6 and depression, observational studies cannot confirm causality." (PMID 30244217, 2018). "For example, genetic polymorphisms in IL-10 and IL-6 have been associated with a higher risk of suffering depression." (PMID 30662368, 2018). "Our study found that supplementation with EPA-rich fish oil in particular resulted in reduced concentrations of IL6 and TNFα, inflammatory cytokines that have been associated with major depression in other studies." (PMID 29940888, 2018).